CCDC69 (coiled-coil domain containing 69)
Description:
May act as a scaffold to regulate the recruitment and assembly of spindle midzone components. Required for the localization of AURKB and PLK1 to the spindle midzone.
Synonyms: FLJ13705; DKFZP434C171
Tractability: Antibody: the Human Protein Atlas places it where antibodies can reach. PROTAC: its protein half-life has been measured.
Gene: Protein-coding gene on chromosome 5 (151,181,052 to 151,224,124, reverse strand). Ensembl gene ENSG00000198624.
Subcellular location: Cytoplasm, cytoskeleton, spindle; Midbody
Subcellular location (Human Protein Atlas): Plasma membrane; Actin filaments; Golgi apparatus
Gene Ontology:
Molecular function: microtubule binding
Biological process: spindle midzone assembly
Cellular component: midbody; spindle midzone; cytoplasm; nucleus; spindle
Genetic constraint (gnomAD): Loss-of-function variants: 32 observed, 36.41 expected, observed/expected ratio (o/e) 0.88, 90% interval 0.66 to 1.18. The upper end of that interval is the gene's LOEUF score, 1.18, which puts it in group 5 of 6, group 1 being the genes least tolerant of losing a copy. Missense variants: 341 observed, 332.87 expected, observed/expected ratio (o/e) 1.02, 90% interval 0.94 to 1.12. Synonymous variants: 131 observed, 132.96 expected, observed/expected ratio (o/e) 0.99, 90% interval 0.85 to 1.14.
Homologues: Orthologues: macaque CCDC69 (97% identical), pig CCDC69 (79% identical), dog CCDC69 (77% identical), guinea pig CCDC69 (71% identical), tropical clawed frog ccdc69 (42% identical), rat Ccdc69 (36% identical), mouse Ccdc69 (35% identical). Paralogues in human: MTUS2 (30% identical), MTUS1 (29% identical).
Diseases named in the same sentence as CCDC69 in open-access papers:
CCDC69 is named in the same sentence as 24 diseases in open-access papers, as found by Europe PMC text mining. Sharing a sentence is not in itself a finding about the gene and the disease. The quoted sentences say what the papers report.
ovarian carcinoma (7 papers, 2017 to 2025). A malignant neoplasm originating from the surface ovarian epithelium. "Previous studies have shown that specific gene mutations are associated with higher platinum drug sensitivity in many cancers, such as CCDC69 mutation in ovarian cancer, ERCC2 mutation in bladder cancer, and BRCA mutation in pancreatic cancer." (PMID 35087829, 2021). "Recent studies showed that CCDC69 also functions in ovarian cancer, colon cancer, gastric cancer, breast cancer, and lung cancer." (PMID 37828454, 2023). "In the present study, CRISPR/Cas9 technology was applied to knock out CCDC69 in ovarian cancer A2780cis and SKOV3 cells." (PMID 29254192, 2017). "A2780cis CCDC69-/- #26 cells had 2.5-fold lower IC50 of cisplatin than A2780cis wildtype cells (p <0.001), suggesting that depletion of CCDC69 resensitized the cisplatin-induced cytotoxicity in the cisplatin-resistant ovarian cancer cells." (PMID 29254192, 2017). "In conclusion, we provide the first evidence that the depletion of CCDC69 reversed platinum resistance in ovarian cancer cells." (PMID 29254192, 2017). "Collectively, these findings clearly indicate that CCDC69 is crucial for cisplatin-induced apoptosis in ovarian cancer cells." (PMID 29254192, 2017). "Thus, our study provide knowledge about the role of CCDC69 in chemoresistance of ovarian cancer and provide us further clue develop new therapeutic strategy for ovarian cancer patients." (PMID 30651135, 2019). "However, the studies on the role of coiled-coil domain-containing 69 (CCDC69) in ovarian cancer were limited." (PMID 30651135, 2019). "Moreover, survival analysis using ovarian cancer microarray datasets (GSE9891 and GSE17260) indicated a significant association between high CCDC69 expression and better patient survival in the PrognoScan database (p = 0.033 and p = 0.044, respectively)." (PMID 30651135, 2019). "To determine whether downregulation of CCDC69 expression is associated with DNA methylation, we initially analyzed the statuses of the CCDC69 methylation in human ovarian cancer in TCGA." (PMID 29254192, 2017). "As it was demonstrated that, both DNA methylation and histone deacetylation may be responsible for mediating CCDC69 gene expressions in ovarian cancer cells." (PMID 29254192, 2017). "In addition to finding evidence of CCDC69 silencing led to cisplatin sensitivity in ovarian cancer cells, the bisulfite sequencing data showed that CCDC69 promotor region was heavily methylated in A2780 and A2780cis ovarian cancer cells." (PMID 29254192, 2017). "However, little functional study was performed to study the function of CCDC69 in the chemoresistance of ovarian cancer." (PMID 29254192, 2017). "Taken together, these results imply that repressed expression of CCDC69 in certain ovarian cancer cell lines may due to both DNA methylation and histone deacetylation." (PMID 29254192, 2017). "To know if CCDC69 plays a crucial role of in cisplatin resistance, we assessed the difference in expression of CCDC69 between cisplatin-resistant ovarian cancer cells A2780cis and cisplatin-sensitive ovarian cancer cells A2780 by real-time quantitative PCR and western blotting." (PMID 29254192, 2017).
ovarian carcinoma (continued). "Knockout of CCDC69 also induced cisplatin-induced cytotoxicity and apoptosis in SKOV3 ovarian cancer cells." (PMID 29254192, 2017).
breast carcinoma (3 papers, 2020 to 2023). "This study demonstrated the associations of CCDC69 with clinical features, immune infiltration, and immunotherapy in breast cancer." (PMID 37828454, 2023). "Diglyceride acyltransferase-2 (DGAT2) and coiled-coil domain-containing protein 69 (CCDC69) are two mRNAs that are lowly expressed in Her2-positive breast cancer and are involved in the risk scoring system." (PMID 32322168, 2020). "More surprisingly, both DGAT2 and CCDC69 have CNV mutations in Her2-positive breast cancer; DGAT2 expression increases as copy number increases, whereas an increase or increase in CCDC69 copy number results in a decrease in its expression." (PMID 32322168, 2020). "Higher CCDC69 expression was associated with a better breast cancer prognosis." (PMID 37828454, 2023). "We further applied IHC staining to detect CCDC69 expression in a total of 101 breast cancer samples with clinical follow-up data, and found that the median follow-up time was 64.87 months." (PMID 37828454, 2023). "The expression and prognostic significance of CCDC69 in breast cancer were comprehensively analyzed by quantitative real-time PCR, immunohistochemical staining and various databases." (PMID 37828454, 2023). "We performed comprehensive analysis in TCGA database to analyze the correlations between CCDC69 expression and immune cells in breast cancer." (PMID 37828454, 2023). "In conclusion, the upregulation of CCDC69 was correlated with favorable prognosis and immunotherapy benefits for breast cancer patients." (PMID 37828454, 2023). "CCDC69 expression was a reliable predictor for the response status of two therapeutic strategies in breast cancer." (PMID 37828454, 2023). "In a word, CCDC69 was downregulated in breast cancer, and it was correlated with a better clinical prognosis." (PMID 37828454, 2023). "Our results demonstrated that CCDC69 regulated multiple immunity-related mechanisms and affected the immune cell infiltration, especially T cells and DC cells, in breast cancer." (PMID 37828454, 2023). "We also found that CCDC69 was significantly upregulated after exposure to interferon (IFN)-gamma in 4T1 cells (breast cancer) and LLC cells (lung cancer) in vitro." (PMID 37828454, 2023). "Univariate Cox regression analysis demonstrated that CCDC69 expression level was an independent variable (high versus low, HR = 0.635 95%CI (0.458–0.881), p = 0.007) to predict the OS of breast cancer patients." (PMID 37828454, 2023). "We found that CCDC69 was a downregulated gene in breast cancer tissues compared with normal tissues, and demonstrated the prognosis value of CCDC69 and its protective effects on breast cancer from multiple aspects." (PMID 37828454, 2023). "Our results indicated that the CCDC69 was downregulated in ER/PR + breast cancer samples, while the upregulation of CCDC69 was correlated with high level of TILs, especially T cells, in breast cancer." (PMID 37828454, 2023). "Our research revealed the clinical significance of CCDC69 in breast cancer and validated the critical roles of CCDC69 in the tumor immune infiltration and immunotherapy responses." (PMID 37828454, 2023). "All these findings pointed to a favorable prognostic value of CCDC69 in breast cancer." (PMID 37828454, 2023). "Multiple Cox regression analysis also revealed that CCDC69 expression level was an independent factor (high versus low, HR = 0.511, 95%CI (0.312–0.836), p = 0.007) of the OS of patients with breast cancer after adjustment for age, TNM stage, PAM50 classification, and radiation therapy status." (PMID 37828454, 2023). "Currently, the relationships between CCDC69 and immune infiltration or immunotherapy in breast cancer remain unclear." (PMID 37828454, 2023). "These outcomes revealed that CCDC69 functioned as an immunoregulatory factor in breast cancer." (PMID 37828454, 2023).
breast carcinoma (continued). "CCDC69 is expected to be an effective biomarker to predict the survival of breast cancer patients, facilitating the early diagnosis based on molecular subtypes, histological subtypes as well as lymph nodes metastasis of breast cancer." (PMID 37828454, 2023). "The specific roles of CCDC69 in the biological processes of neutrophils and mast cells in breast cancer are still under exploration, and future study could analyze the function of the both cells in breast cancer." (PMID 37828454, 2023). "In our study, the expression of DGAT2 and CCDC69 in Her2-positive breast cancer was decreased and was closely related to patient prognosis; thus, they could be used as biomarkers to evaluate the condition of patients." (PMID 32322168, 2020). "Moreover, the relationships between CCDC69 and immune infiltration and immunotherapy response in breast cancer remains unclear." (PMID 37828454, 2023). "The mRNA of CCDC69 was downregulated in breast cancer tissues compared with normal tissues." (PMID 37828454, 2023). "Moreover, due to the limitation of bioinformatics technology and data in the database, there has not been a comparative analysis of CCDC69 expression levels in various breast cancer subtypes in this study." (PMID 35910470, 2022).
melanoma (3 papers, 2022 to 2023). A malignant, usually aggressive tumor composed of atypical, neoplastic melanocytes. "On the contrary, the CCDC69 expression was relatively low expressed in the endometrium, glioma, lymphoma Hodgkin, mesothelioma, osteosarcoma, melanoma, Ewings sarcoma, kidney, lung small cell, neuroblastoma." (PMID 35910470, 2022).
bladder cancer (2 papers, 2021 to 2023). "In the ICI-treated patient cohort of Camoip database, we found that higher expression level of CCDC69 could predict better immunotherapy benefits in bladder cancer, as shown by OS (HR = 0.76, 95%CI (0.58–0.98), p = 0.034)." (PMID 37828454, 2023).
colon cancer (2 papers, 2023). "For instance, CCDC69 has been associated with immune infiltration and serves as a prognostic marker in breast and colon cancers." (PMID 37547318, 2023).
gastric cancer (2 papers, 2021 to 2023). A primary or metastatic malignant neoplasm involving the stomach.
carcinoma in situ (1 paper, 2022). "The results showed that CCDC69 expression was significantly lower in cancer samples than in normal tissues, and was significantly lower in highly invasive BC than in carcinoma in situ." (PMID 35910470, 2022).
endometrium (1 paper, 2023). "We found that CCDC69 was differently expressed in 18 cancer types with statistical significance in lung, blood, brain, breast, skin, colon, ovary, pancreas, esophagus, tongue, adrenal gland, prostate, kidney, bladder, liver, vulva, vagina, and endometrium cancers." (PMID 37828454, 2023).
invasive breast carcinoma (1 paper, 2022). A carcinoma that infiltrates the breast parenchyma. "CCDC69 mRNA levels were obviously lower in invasive breast carcinoma tissues compared with adjacent normal tissues." (PMID 35910470, 2022).
metastatic melanoma (1 paper, 2023). A melanoma that has spread from its primary site to another anatomic site. "As for the immunomodulatory mechanism of SNTB2, SLC1A4, LAMP3 and CCDC69 in metastatic melanoma or macrophages, it was not specifically elucidated, though it is still a promising research direction." (PMID 37762054, 2023).
multiple myeloma (1 paper, 2022). "The CCDC69 expression was relatively highly expressed in B-cell_ALL, multiple myeloma, CML, AML, T-cell_ALL, upper aerodigestive, pancreas, colorectal, and esophagus." (PMID 35910470, 2022).
Myocardial fibrosis (1 paper, 2025). "Using Masson, H&E, and IF (Collagen III and α-SMA) staining, we confirmed that CCDC69 overexpression inhibited the extent of DOX-induced myocardial fibrosis and inflammation mediated by CDC20." (PMID 40045239, 2025).
periodontitis (1 paper, 2023). An acute or chronic inflammatory process that affects the tissues that surround and support the teeth. "The LASSO analysis results showed that two overlapping genes (CCDC69 and CXCL12) were the optimal shared diagnostic biomarkers for periodontitis and IgAN." (PMID 36793719, 2023). "Finally, two overlapping genes (CCDC69 and CXCL12) were discovered to be the optimal shared diagnostic biomarkers for periodontitis and IgAN." (PMID 36793719, 2023). "Therefore, both CXCL12 and CCDC69 have good predictive properties for periodontitis and IgAN." (PMID 36793719, 2023). "By taking the intersection of WGCNA important module genes and DEGs, we found that the SPAG4, CCDC69, KRT10, CXCL12, HPGD, CLDN20 and CCL187 genes were the most important cross-talk genes between periodontitis and IgAN." (PMID 36793719, 2023). "In this study, CCDC69 and CXCL12 had a significant positive correlation with central memory CD4+ T cells and immature B cells in both periodontitis samples and IgAN samples." (PMID 36793719, 2023). "The SPAG4, CCDC69, KRT10, CXCL12, HPGD, CLDN20 and CCL187 genes were the most important cross-talk genes between periodontitis and IgAN." (PMID 36793719, 2023). "Both CCDC69 and CXCL12 were upregulated in periodontitis and IgAN." (PMID 36793719, 2023). "By taking the intersection of WGCNA important module genes and DEGs, we found that the SPAG4, CCDC69, KRT10, CXCL12, HPGD, CLDN20 and CCL187 genes were the most important cross-talk genes between periodontitis and IgAN, and these genes may be related to kinase regulator activity." (PMID 36793719, 2023).
cancer (8 papers, 2017 to 2023). A tumor composed of atypical neoplastic, often pleomorphic cells that invade other tissues. "As a molecule controlling the assembly of central spindles and recruitment of midzone component, coiled-coil domain-containing protein 69 (CCDC69) plays an important role in multiple cancers." (PMID 37828454, 2023). "Up to date, a large number of studies have uncovered multiple genes can serve as biomarkers for immunotherapy response in BrCa or other cancer types, such as CCDC69, TIMM8A, and ACE2." (PMID 36583022, 2022). "CCDC69 was decreased in BC and 16 other types of cancer tissues than in corresponding normal tissues." (PMID 35910470, 2022). "We postulated that the cancer cells with low expression of CCDC69 under combined treatment with cisplatin and HDAC inhibitor would further increase the efficacy of cisplatin treatment." (PMID 29254192, 2017). "CCDC69 was downregulated in the 18 types of cancer tissues compared with adjacent normal tissues." (PMID 37828454, 2023). "In addition, CCDC69 mRNA expression level was found to be downregulated in cancers of the ovary, breast, esophagus and small intestine compared with corresponding normal tissues as shown in public database." (PMID 29254192, 2017). "Therefore, CCDC69 may be a promising target for therapeutic application in cancer." (PMID 30651135, 2019).
tumor (8 papers, 2017 to 2025). "Here, we evaluated CCDC69 expression in tumor immune microenvironment-associated immune cells using single-cell transcriptomes obtained from 11 tumors pretreated with atezolizumab plus paclitaxel." (PMID 37828454, 2023). "Changes in CCDC69 expression resulting from ATRX mutation may influence tumor progression and immune responses in LMS tissue." (PMID 40495762, 2025). "A machine learning study based on TCGA database showed that CCDC69 expression is negatively correlated with tumor purity." (PMID 37828454, 2023). "CCDC69 was demonstrated to be positively correlated with stromal fraction, tumor infiltrating lymphocyte (TIL) fraction, and lymphocyte infiltration signature score." (PMID 37828454, 2023). "In this study, the relationship between CCDC69 expression levels and tumor clinical characteristics were analyzed using RNA-seq information in BC samples from the TCGA database." (PMID 35910470, 2022). "The correlation between the expression of CCDC69 and the number of tumor-infiltrating lymphocytes was confirmed by interaction analysis of TIMER and GEPIA." (PMID 35910470, 2022). "In vivo model of targeting CCDC69 and clinical setting of measuring CCDC69 expression in circulating tumor cells are needed for additional in-depth studies." (PMID 29254192, 2017). "CCDC69 is typically expressed at low levels in tumor tissues." (PMID 40045239, 2025). "Therefore, it was necessary to further verify the correlation between CCDC69 and tumor immune microenvironment." (PMID 35910470, 2022). "CCDC69 mRNA levels were inversely correlated with tumor size, pathological stage of BC patients." (PMID 35910470, 2022). "Thus, our study puts insights into understanding the potential role of CCDC69 in tumor immunology and its potential as a BC biomarker." (PMID 35910470, 2022). "The expression of CCDC69 is positively correlated with immune cells (B cells, CD8+ cells, neutrophils, dendritic cells and lymphocytes) around the tumor, which can reflect the infiltration of immune cells." (PMID 36793719, 2023).
CCDC69 also shares sentences with these, for which no sentence is quoted: Ewing sarcoma (1 paper); glioma (1); lung carcinoma (1); lymphoma Hodgkin (1); mesothelioma (1); neuroblastoma (1); osteosarcoma (1); pancreatic cancer (1); Tay-Sachs disease (1).